GOLGA8S (golgin A8 family member S)
Tractability: No criterion of Open Targets' tractability assessment is met for any kind of drug.
Gene: Protein-coding gene on chromosome 15 (23,354,748 to 23,368,341, forward strand). Ensembl gene ENSG00000261739.
Gene Ontology:
Biological process: Golgi organization
Cellular component: cis-Golgi network; Golgi cis cisterna; Golgi cisterna membrane; Golgi apparatus
Genetic constraint (gnomAD): Loss-of-function variants: 11 observed, 12.48 expected, observed/expected ratio (o/e) 0.88, 90% interval 0.55 to 1.45. The upper end of that interval is the gene's LOEUF score, 1.45, which puts it in group 6 of 6, group 1 being the genes least tolerant of losing a copy. Missense variants: 154 observed, 147.29 expected, observed/expected ratio (o/e) 1.05, 90% interval 0.92 to 1.2. Synonymous variants: 63 observed, 53.58 expected, observed/expected ratio (o/e) 1.18, 90% interval 0.96 to 1.45.
Homologues: Orthologues: mouse Golga2 (47% identical), dog GOLGA2 (45% identical), tropical clawed frog golga2 (35% identical), zebrafish golga2 (31% identical), Drosophila melanogaster GM130 (22% identical), Caenorhabditis elegans golg-2 (19% identical), rat Golga2l1 (5% identical). Paralogues in human: GOLGA8G (93% identical), GOLGA8F (91% identical), GOLGA8M (85% identical), GOLGA8J (84% identical), GOLGA8H (84% identical), GOLGA8N (83% identical), GOLGA8O (83% identical), GOLGA8Q (83% identical), GOLGA8T (83% identical), GOLGA8K (83% identical), GOLGA8R (82% identical), GOLGA8A (69% identical), and 6 more.